TLR7 (toll like receptor 7)
Diseases named in the same sentence as TLR7 in open-access papers (continued):
Sharing a sentence is not in itself a finding about the gene and the disease.
plague (2 papers, 2017 to 2024). Plague is a severe bacterial infection caused by the gram-negative bacterium Yersinia pestis. "In the murine plague model, TLR7 was a significant contributor to the expression of serum IFN-β, whereas MyD88 was not." (PMID 28847850, 2017). "Together, these data demonstrate that an atypical TLR7 signaling pathway contributes to type I IFN expression during Y. pestis infection and suggest that the TLR7-driven type I IFN response plays an important role in determining the outcome of plague." (PMID 28847850, 2017). "We observed a TLR7-dependent elevation of serum IFN-β levels in murine models of pneumonic and septicemic plague, and Tlr7−/− mice appeared to have controlled disease in the liver, probably through a more effective neutrophil response." (PMID 28847850, 2017). "We identified an atypical TLR7 signaling pathway induced by Y. pestis that is an important contributor to IFN-β expression and characterized its role in the progression of plague." (PMID 28847850, 2017). "Genetic data suggest that TLR7 contributes to inflammatory pathology during plague, as mice lacking Tlr7 were more resistant to Y. pestis infection with enhanced inflammatory pathology evident in the lungs and liver compared to infected wild-type mice." (PMID 38389313, 2024). "As a consequence of the bifunctional role of TLR7, there was no significant survival difference between WT and mutant mice in the pneumonic plague model." (PMID 28847850, 2017).
pneumococcal infection (2 papers, 2009 to 2020). Infections with bacteria of the species streptococcus pneumoniae. "To ascertain if the phenotype of 3d mice could be recapitulated by the simultaneous absence of multiple endosomal receptors, we developed TLR7/9/13 triple KO mice and tested them for susceptibility to pneumococcal infection." (PMID 32209688, 2020). "Thus, control of pneumococcal infection in the central nervous system apparently depends on the additive, cooperative activity of multiple cell surface (TLR2) and endosomal (TLR7, TLR9, and TLR13) receptors." (PMID 32209688, 2020). "To identify relevant TLRs, we tested mice lacking TLR3, TLR7, TLR9, or TLR13, as well as TLR7/9−/− double knockout (KO) mice, for their ability to control pneumococcal infection." (PMID 32209688, 2020). "Indeed, lung-resident alveolar macrophages are the first line of cellular defence for pneumococcal infections and these are not depleted by the antibody RB6-8C5 and most likely also not by TLR7 triggering." (PMID 19290047, 2009).
pneumonitis (2 papers, 2024 to 2025). An inflammatory process affecting the lung parenchyma. "Pneumonitis severity was worse in female versus male mice, and this was associated with increased expression of X-linked TLR7." (PMID 39808500, 2025).
prion disease (2 papers, 2020 to 2022). A transmissible disease that is caused by a protein that is able to induce abnormal folding of normal cellular proteins, leading to characteristic spongiform brain changes, which are associated with neuronal loss without an inflammatory response. "The upregulation of TLR7 has been previously reported in mouse models of prion disease and in human patients." (PMID 35408945, 2022).
pulmonary tuberculosis (2 papers, 2017 to 2021). A bacterial infection that affects the lungs and is caused by Mycobacterium tuberculosis. "TLR7 and TLR8 recognize single-stranded RNA and RNA degradation products from viruses and bacteria, and polymorphisms in TLR7 and 8 have been associated with increased susceptibility to pulmonary tuberculosis." (PMID 28806745, 2017).
renal carcinoma (2 papers, 2022 to 2024). A carcinoma arising from the epithelium of the renal parenchyma or the renal pelvis. "In order to better characterize the effect of HSD11B1 inhibition on the antitumor immune response in the context of TLR7 stimulation, we tested the impact of HSD11B1 activity on the capacity of mouse dendritic cells to initiate an antitumor immune response against renal cancer cells." (PMID 38170044, 2024).
respiratory failure (2 papers, 2022 to 2024). The significant impairment of gas exchange within the lungs resulting in hypoxia, hypercarbia, or both, to the extent that organ tissue perfusion is severely compromised. "Different human polymorphisms have an impact on clinical outcomes: sequence changes in ApoE, TLR7, TMEM189-UBE2V1, as well as SLC6A20, LZTFL1, CCR9, FYCO1, CXCR6, XCR1, have been associated with severe disease outcomes as well as respiratory failure." (PMID 35207458, 2022).
Rotavirus infection (2 papers, 2013 to 2017). Infection with any of the rotaviruses. "TLR7 signaling in plasmacytoid DCs (pDCs) primes B and T cell activation via IFN-I secretion in rotavirus infections; however, inhibition of TLR7 is able to block this process from occurring and prevent acceleration of T1D following infection." (PMID 29018409, 2017). "Rotavirus recognition by PRRs may be cell type-specific, and other endosomal or surface membrane-associated PRRs such as TLR3, TLR7, and TLR9 have been implicated in stimulating innate responses to rotavirus infection, although more definitive studies on these topics are required." (PMID 23359266, 2013).
Salmonella Infections (2 papers, 2018 to 2019). Infections with bacteria of the genus SALMONELLA. "Considered to the function of TLR2, TLR4, TLR7, TNF2, IL8, and IL18, it was revealed that the immune defense would been inhibited for REV infection through salmonella infection, NOD-like receptor, Toll-like receptor and MAPK-AP1 pathways." (PMID 29410628, 2018). "Moreover, TLR2, TLR4, TLR7, and IL8 were enriched in Toll-like receptor pathway, IL8 and IL18 were enriched in the NOD-like receptor pathway, and TLR4, IL8, and IL18 were enriched in the salmonella infection pathway." (PMID 29410628, 2018).
sarcoidosis (2 papers, 2010 to 2023). Sarcoidosis is a multisystemic disorder of unknown cause characterized by the formation of immune granulomas in involved organs. "Enriched genes including MPO (myeloperoxidase), CXCL11, IL1A, CXCL10, FCGR3B, IL1B, TTN (titin), BATF2, VIP (vasoactive intestinal peptide), TLR3, CCR2, TLR7, and CR1 wereclosely related to sarcoidosis." (PMID 38137330, 2023). "An upregulation in TLR-7 and -9 mRNA expression was detected in IPF (P = 0.05) and sarcoidosis (P = 0.05), respectively, when compared to controls." (PMID 20937083, 2010).
Skin Cutaneous Melanoma (2 papers, 2023 to 2025). "To confirm our in silico prediction, we performed immunohistochemistry and multiplex immunofluorescence for TLR7/8 in an independent cohort of patients with cutaneous melanoma." (PMID 39849091, 2025).
steatosis (2 papers, 2016 to 2017). Increased lipid within the cytoplasm of cells. "Small-scale preliminary study also showed that TLR7 expression was downregulated in liver biopsy specimens from chronic HBV patients (LB_7-18) (n = 12) compared to control steatosis individuals (LB_1-6) (n = 6)." (PMID 28088184, 2017).
visceral leishmaniasis (2 papers, 2019 to 2023). A severe form of leishmaniasis characterized by irregular bouts of fever, substantial weight loss, swelling of the spleen and liver, and anemia (which may be serious). "In fact, recent evidence associated TLR7 activation with disease exacerbation of visceral leishmaniasis due to L. donovani in mice." (PMID 31806038, 2019). "In our previous work, we have shown that CD4+ T cells are capable of sensing inflammatory tissue damage–derived DAMPs via TLR7 in a murine model of visceral leishmaniasis." (PMID 37227774, 2023).
age (1 paper, 2017). A temporal measurement of the time period elapsed since an identifiable point in the life cycle of an organism. "Our study demonstrates that renal small RNAs from aged rats induce pro‐inflammatory processes via the activation of the TLR7/IKKα/β/JNK/NF‐κB signaling pathway, and highlights its causative role as a possible therapeutic target in age‐related chronic renal inflammation." (PMID 28665028, 2017).
alcoholic liver diseases (1 paper, 2015). A disorder caused by damage to the liver parenchyma due to alcohol consumption. "A potential mechanism involving TLR9 has been shown to cause increased IgA levels in patients with alcoholic liver disease, and TLR-7-mediated plasma cell activation has also been reported to induce Ig synthesis." (PMID 25826264, 2015).
alcoholic neuropathy (1 paper, 2019). "Given that let-7-loaded microvesicles promote increased vulnerability to alcoholic neuropathy by activating TLR7 in neurons, exosomal miRNAs may contribute to activation of PRRs and neutrophil survival." (PMID 30683126, 2019).
alveolitis (1 paper, 2023). "This histological analysis indicates that RSV infection induces an infiltration of cells into the deep airway spaces of the lung, which is likely to be TLR7-dependent, leading to chronic alveolitis and enhanced bronchiolar inflammation." (PMID 37795093, 2023). "Additionally, RSV infection resulted in an insignificant trend towards chronic alveolitis at 42 dpi in WT mice but this was not evident in TLR7 KO mice." (PMID 37795093, 2023).
aortic valve disease (1 paper, 2025). "The present study builds upon our previous findings in heart tissue from patients with advanced coronary artery disease and aortic valve disease, which demonstrated increased expression of TLR1, TLR3, and TLR7, along with elevated levels of their downstream signaling mediators." (PMID 39828779, 2025).
autoimmune encephalitis (1 paper, 2025). Inflammation of the brain secondary to an immune response triggered by the body itself. "However, X genes also harbor immune-related functions that exacerbate phenotypes, as noted with Tlr7 in the brains of aging male mice and Kdm6a in lymphocytes of female mice in an experimental model of autoimmune encephalitis." (PMID 40043106, 2025).
autoimmune glomerulonephritis (1 paper, 2012). An autoimmune form of glomerulonephritis (disease). "Demaria and colleagues reported that Tlr8−/− mice develop autoimmune glomerulonephritis due to excessive TLR7 expression and activation, and that this was attenuated in double Tlr7−/−/Tlr8−/− mice." (PMID 22848646, 2012).
autoimmune uveitis (1 paper, 2021). An autoimmune form of uveitis (disease). "Our findings highlight an immunomodulatory role of RPE TLR7 in EAU development and provide a potential therapeutic strategy for autoimmune uveitis." (PMID 35069523, 2021).
B cell lymphoma (1 paper, 2025). "TLR7, despite being expressed in B cell lymphoma, does not associate with IgM." (PMID 39868594, 2025).
Behcet disease (1 paper, 2022). A chronic, relapsing, multisystemic vasculitis characterized by mucocutaneous lesions, as well as articular, vascular, ocular and central nervous system manifestations. "Furthermore, copy number variants in TLR7 also appear to be associated with an increased risk of Behcet’s disease, with at least one contributing to risk in males and two contributing to risk in females." (PMID 38983565, 2022). "One copy of TLR7 had a significantly increased frequency in male patients (p = 0.021) with Behcet disease, and two copies in female patients (p = 0.048)." (PMID 38983565, 2022).
breast adenocarcinoma (1 paper, 2025). "Among the increased transcripts were those of inflammation/innate immunity-related genes Tnf, Lta, Ltb, Light and Tlr7, many of which were also predicted by our pathway analysis of clinical specimens comparing TLS-rich versus TLS-free breast adenocarcinomas." (PMID 40897896, 2025).
bronchopneumonia (1 paper, 2017). Acute inflammation of the walls of the terminal bronchioles that spreads into the peribronchial alveoli and alveolar ducts. "In contrast, 69% of Tlr7−/− mice had moderate to severe focal bronchopneumonia, with large areas of neutrophilic infiltrates and bacterial growth in the alveolar space, while other sections of the lung were unaffected." (PMID 28847850, 2017). "In the lungs, the TLR7 host response played a significant role in preventing the development of bronchopneumonia, while in the liver, the suppression of the neutrophilic response through TLR7 contributed to disease." (PMID 28847850, 2017). "In mice with TLR7, perhaps an early type I IFN response that dampened neutrophil recruitment in the lungs reduced tissue damage, which resulted in fewer WT mice developing bronchopneumonia." (PMID 28847850, 2017).
cardiac hypertrophy (1 paper, 2022). "The induction of cardiac hypertrophy by the serum or splenocytes from R848-treated TC mice suggested that the cardiovascular pathology in R848-treated TC mice may result at least in part from their enhanced immune response to TLR7 activation." (PMID 35860280, 2022).
Cerebral ischemia (1 paper, 2015). Restriction of arterial blood supply to the brain associated with insufficient oxygenation to support the metabolic requirements of the tissue. "Additionally, compared with type I IFN (IFNAR)+/+ mice, the protective effect of cerebral ischemia in IFNAR-/- mice with GDQ preconditioning was significantly decreased, indicating that TLR7 mediates the protection of cerebral ischemia through its cognate receptor IFNAR." (PMID 25928750, 2015).
Chagas disease (1 paper, 2018). A parasitic infection caused by Trypanosoma cruzi. "Patients with different clinical manifestations of Chagas disease showed similar expression of TLR1, TLR3, TLR4, TLR5, TLR6, TLR7 and TLR9 mRNA." (PMID 30044791, 2018). "On the other hand, patients with different clinical manifestations of Chagas disease showed similar mRNA expression levels of TLR1, TLR3, TLR4, TLR5, TLR6, TLR7 and TLR9." (PMID 30044791, 2018).
childhood asthma (1 paper, 2024). "A significant correlation was found between TLR7 single nucleotide polymorphism (SNP) and childhood asthma." (PMID 38341589, 2024).
chorioamnionitis (1 paper, 2012). A morphologic finding indicating inflammation of the fetal sac membranes. "For instance, of the 6 women with chorioamnionitis none had increased levels of TLR3, only 1 had increased levels of TLR7, and 2 for TLR8." (PMID 22848646, 2012).
Chronic colitis (1 paper, 2024). A chronic inflammatory disease of the large intestine (colon, cecum and rectum). "Our findings reveal that TLR7 protects from the development of colonic inflammation in both acute and chronic colitis." (PMID 39464882, 2024). "To determine if T cell intrinsic TLR7 signaling contributes to the development of chronic colitis, we transferred CD4+ CD45RBhi naive T cells isolated from wild-type (WT) or Tlr7-/- mice into Rag1-/- mice and monitored for development of inflammatory disease." (PMID 39464882, 2024).
chronic obstructive pulmonary disease (1 paper, 2023). A chronic and progressive lung disorder characterized by the loss of elasticity of the bronchial tree and the air sacs, destruction of the air sacs wall, thickening of the bronchial wall, and mucous accumulation in the bronchial tree. "Toll-like receptor 7 (TLR7) is known for eliciting immunity against single-stranded RNA viruses, and is increased in both human and cigarette smoke (CS)-induced, experimental chronic obstructive pulmonary disease (COPD)." (PMID 37963864, 2023).
cystitis (1 paper, 2024). Inflammation of the urinary bladder. "TLRs have also been implicated in IC/BPS pathogenesis; TLR7 was observed to be upregulated in bladder biopsies of Hunner-type IC patients and in TLR7 agonist-induced cystitis in mice." (PMID 38997336, 2024).
Duchenne muscular dystrophy (1 paper, 2011). Duchenne muscular dystrophy (DMD) is a neuromuscular disease characterized by rapidly progressive muscle weakness and wasting due to degeneration of skeletal, smooth and cardiac muscle. "TLR3 and TLR7 are elevated in inflammatory myopathies as is TLR7 in muscles of Duchenne muscular dystrophy patients." (PMID 21850221, 2011).
Dysmenorrhea (1 paper, 2017). Pain during menstruation that interferes with daily activities. "After statistical analysis confirmed that: The gene expression of TLRS (TLRS = TLR1 + TLR2 + TLR3 + TLR4 + TLR5 + TLR6 + TLR7 + TLR8 + TLR9) in severe and moderate dysmenorrhea group was significantly higher than that in minimal dysmenorrhea group in EU and EC (P < 0.05 or P < 0.01)." (PMID 28779087, 2017).
E. coli) infection (1 paper, 2026). "We utilized an in vitro model of gram-negative bacterial (E. coli) infection to study whether TLR7/8 pre-stimulation influence peri-phagocytic reactions." (PMID 41974867, 2026).
encephalomyelitis (1 paper, 2026). Inflammation of the brain and the spinal cord. "Moreover, 2D2TgDcir -/- Tlr7 -/- mice developed less EAE-like encephalomyelitis." (PMID 42256301, 2026).
endometrial disorder (1 paper, 2018). A non-neoplastic or neoplastic disorder that affects the endometrium. "TLR-7/9 and IL-6/8 were shown to be related to endometrial disorders." (PMID 30322386, 2018).
endometriosis (1 paper, 2025). The growth of functional endometrial tissue in anatomic sites outside the uterine body. "We observed markedly higher expression of TLR2, TLR3, TLR4, TLR7, TLR8, and TLR9 on CD4+, CD8+, and CD19+ lymphocytes in the endometriosis group, indicating their active participation in modulating immune responses in the disease setting." (PMID 40862752, 2025).
familial chilblain lupus (1 paper, 2025). An instance of Chilblain lupus that is caused by an inherited modification of the individual's genome. "While UNC93B1 p.Ile317Met (c.325G >C) associates with gain of TLR7 activity and jSLE, UNC93B1 p.Leu330Arg, p.Arg466Ser, and p.Arg525Pro primarily associate with gain of TLR8 activity, isomorphic TLR7 activity and familial chilblain lupus." (PMID 41410901, 2025).
fasciolosis (1 paper, 2019). "We also observed the activation of TLR7 in the time period from the acute to chronic fasciolosis in cattle." (PMID 31555289, 2019).
Flavivirus Infections (1 paper, 2016). Infections with viruses of the genus FLAVIVIRUS, family FLAVIVIRIDAE. "However, it was recently reported that TLR7 activation by RNA virus may enhance Nox activation and oxidative stress, and this may also be true for Flavivirus infection." (PMID 27610098, 2016). "During flavivirus infection, IFN production is stimulated by RIG-I, MDA5, TLR3, and TLR7 triggering a variety of cell responses affecting cellular physiology and virus replication (Muñoz-Jordán and Fredericksen, 2010)." (PMID 27610098, 2016).
genital herpes (1 paper, 2018). Herpes simplex infection of the genitals, most commonly caused by the herpes simplex-2 virus. "However, in the guinea pig model for genital herpes, the TLR7 agonist imiquimod potently induced protection." (PMID 29608601, 2018).
gingivitis (1 paper, 2019). A disorder involving inflammation of the gums; may affect surrounding and supporting structures of the teeth. "In brief, all three types of biofilm strongly up-regulated TLR2 mRNA expression; TLR7 was significantly activated by commensal and gingivitis biofilms; TLR4 expression was only clearly increased by gingivitis biofilm; TLRs 3, 5, and 6 were not significantly affected by the biofilms." (PMID 31448244, 2019).
glomerular disease (1 paper, 2023). "Unexpectedly, TLR7 deficiency in CD11c+ cells had no impact on disease, while TLR7 deficiency in CD19+ B cells yielded mild suppression of proteinuria and a trend toward reduced glomerular disease." (PMID 37606042, 2023).
Glucose intolerance (1 paper, 2019). Glucose intolerance (GI) can be defined as dysglycemia that comprises both prediabetes and diabetes. "TLR8ko and WT mice showed similar glucose kinetics, while HFD-fed TLR7/8ko and TLR7ko mice showed improved glucose tolerance compared to their HFD-fed WT controls, suggesting that TLR7-deficiency protects from HFD-induced glucose intolerance." (PMID 31552019, 2019).